ALB (albumin)
Diseases named in the same sentence as ALB in open-access papers (continued):
Sharing a sentence is not in itself a finding about the gene and the disease.
cancer (continued). "Albumin, frequently used to assess nutritional status in cancer patients, is shown to correlate with performance status and OS when combined with lymphocyte levels in the prognostic nutritional index." (PMID 40365347, 2025). "The neutrophil percentage-to-albumin ratio (NPAR) is a promising indicator for predicting outcomes in various cancers." (PMID 40709341, 2025). "Serum albumin (ALB), as an indicator of nutritional status, has been proven to be closely associated with poor prognosis in multiple cancer types." (PMID 40535131, 2025). "The sACR, which stands for the serum albumin-to-creatinine ratio, has major advantages when it comes to detecting cardiotoxicity in cancer patients." (PMID 40095884, 2025). "Several nutritional scoring systems, such as Nutritional Risk Screening (NRS), albumin (ALB), and Prognostic Nutritional Index (PNI), proved to be prognostic factors in cancer patients." (PMID 40216704, 2025). "Serum albumin level and body mass index (BMI), acting as indicators of nutritional status, are commonly applied to predict surgical outcomes in cancer patients." (PMID 40225113, 2025). "Noteworthy examples, such as albumin, lactoferrin, and gelatin nanoparticles, along with peptide-based nanoparticles, demonstrate their broad applicability in both infection control and cancer therapy." (PMID 40343307, 2025). "however, CJME effectively countered this wasting and restored abnormal biochemical parameters such as CK, albumin, triglycerides (TG), cholesterol, high-density lipoprotein (HDL), and low-density lipoprotein (LDL) associated with cancer cachexia." (PMID 40469669, 2025). "Based on these findings, it is clear that basic blood tests like hemoglobin, CRP, and albumin can help screen for cancer in patients with thickened bowel walls seen on scans." (PMID 41011090, 2025). "In cancer, inflammatory cytokines and increased capillary permeability can lead to lower serum albumin levels." (PMID 40941722, 2025). "The high validity of GNRI in predicting outcomes of HCC as well as other cancers has been ascribed to its two components i.e. albumin and body weight." (PMID 40290253, 2025). "Previous studies have identified several hematological parameters that are crucial biomarkers for cancer prognosis, including platelet-to-lymphocyte ratio, prognostic nutritional index, systemic immune inflammation index, and albumin-to-globulin ratio." (PMID 40678069, 2025). "This study investigates the functional impact of Ly6C expression on CD8+ T cells and explores albumin-conjugated IFNβ (Alb-IFNβ) as a strategy to modulate Ly6C expression and improve cancer vaccine efficacy." (PMID 40266123, 2025). "On the one hand, albumin and prealbumin were considered as more frequent markers for accessing nutritional status of cancer patients." (PMID 40806017, 2025). "They demonstrate substantial anti‐inflammatory effects through inhibition of albumin denaturation along with moderate cytotoxicity against cancer cell lines and broad‐spectrum antimicrobial activity." (PMID 39417784, 2025). "Albumin also enhances ingestion of drugs into lysosomal compartments of cancer cells compared to normal cells and has a natural ability to accumulate in areas of inflammation." (PMID 40871005, 2025). "This binding not only stabilizes the photosensitizer but also leverages albumin’s natural transport capabilities to improve preferential uptake in cancer cells and prolong circulation time, thus amplifying therapeutic efficacy." (PMID 41373713, 2025). "PNI represents a combination measure of lymphocyte count and albumin level for the prediction of postoperative prognosis in cancer patients." (PMID 40389774, 2025). "On multivariate analysis, only low serum albumin remained a consistent predictor of wasting among childhood cancer patients." (PMID 40773483, 2025). "Albumin nanoparticles substantially improve cancer cell uptake of phthalocyanine, facilitating lysosomal accumulation and rapid intracellular release." (PMID 41373713, 2025).
cancer (continued). "Human serum albumin, one of the most common protein nanostructures used to deliver nanoparticles, is reported to enhance the anti-cancer and anti-bacterial properties, with least toxicity." (PMID 41211197, 2025). "The eosinophil-to-albumin ratio (EAR) is a less explored yet potentially insightful biomarker in the realm of cancer research and inflammation." (PMID 40256426, 2025). "Although MAOA is the preferred target, NMI must first pass through the blood via albumin, enter the cancer cell, and bind MAOA on the outer mitochondrial surface." (PMID 39904854, 2025). "A range of nutritional and immune markers, including the prognostic nutrition index (PNI), Glasgow prognostic score, and neutrophil-albumin ratio, can be used to identify prognostic survival in cancer patients." (PMID 39673205, 2025). "The advanced lung cancer inflammation index (ALI) prognosticated outcomes across several cancer types, combining body weight, albumin, and neutrophil to lymphocyte ratio (NLR) to evaluate systemic inflammation." (PMID 39464703, 2024). "Both serum albumin and PNI has been widely used to evaluate the risk of postoperative complications, disease progression, and survival in various cancers." (PMID 39529928, 2024). "In conclusion, the glucose to serum albumin ratio (GAR) emerges as a promising prognostic marker for cardiovascular outcomes in cancer patients undergoing anthracycline therapy." (PMID 39660481, 2024). "The serum albumin content in cancer patients usually decreases gradually with the progression of the disease, and studies have confirmed that the decrease of serum albumin indicates poor clinical prognosis." (PMID 38216656, 2024). "Its classification value has already been recognized, and the measured parameters, such as serum albumin, body height, and body weight, have been routinely assessed in cancer patients." (PMID 38580988, 2024). "The top 3 impactful data features are the latest albumin value, stage 4 cancer on diagnosis, and unique number of cancer drugs given." (PMID 38769564, 2024). "Low serum albumin levels reflect both poor nutritional status and an ongoing inflammatory response, which are critical in the management and recovery of cancer patients." (PMID 39529928, 2024). "The distribution of urea, creatinine, sodium and albumin wereslightly skewed towards lower values in patients presenting with advanced cancer." (PMID 38460949, 2024). "In short, while the increase in hemoglobin, albumin and lymphocyte contributes positively to the prognosis in cancer patients, the increase in thrombocyte contributes negatively." (PMID 39061000, 2024). "Variables with p < 0.1 between the low albumin group and the normal group included hemoglobin, type of cancer, ISL stage, lower leg PEV, and whole leg PEV." (PMID 39529928, 2024). "GNRI contains serum albumin and body weight, which are both significant prognostic factors for cancer." (PMID 38669385, 2024). "A database search was performed in Embase, Web of Science, and MEDLINE-PubMed searching for all articles that included keywords relating any form of prognosis of cancer of the primary gastrointestinal (GI) tract to albumin-to-globulin ratio (AGR)." (PMID 38975562, 2024). "Serum albumin has been widely used in assessing patients’ general nutritional health and as a prognostic biomarker for cancer." (PMID 38911864, 2024). "Several studies have confirmed that albumin can effectively predict the prognosis of many malignant tumors." (PMID 39897534, 2024). "In terms of basic research, future studies should further investigate the links between albumin and the pathological mechanisms of cancer to better understand its role in cancer prognosis." (PMID 38500655, 2024). "Albumin-to-globulin ratio (AGR) is a cheap, widely accessible component of common blood work that has been implicated in the prognosis of various cancers." (PMID 38975562, 2024).
cancer (continued). "This evidence underscores the significance of albumin levels as a prognostic biomarker in senior cancer patients, surpassing other potential biomarkers related to liver function." (PMID 39195131, 2024). "An advancement in this field involves developing drugs bound to HSA for intraperitoneal drug delivery, known as albumin-based cancer therapeutics." (PMID 39684376, 2024). "Nab-paclitaxel, a nanoparticle albumin-bound form of paclitaxel, enhances drug delivery to tumors by targeting albumin receptors overexpressed on cancer cells, improving treatment precision and reducing side effects." (PMID 39518676, 2024). "One year later, a kind of albumin nanoparticles loaded with pirarubicin was constructed to treat the occurrence of cancer and the metastasis of tumors." (PMID 38323081, 2024). "Albumin-based drug delivery systems have appeared promising therapeutics in the diagnosis and treatment of cancers." (PMID 39339208, 2024). "Serum albumin is a pivotal component in certain cancer scoring systems, serving as a stabilizing factor in cancer prognosis." (PMID 38500655, 2024). "There are currently several albumin-based nanomedicines tested in clinical trials for potential use as cancer therapeutics." (PMID 39770409, 2024). "In many studies, the affinity of albumin for biodistribution within cancer cells and the uptake of this protein by these cells have been proven." (PMID 38255859, 2024). "Previous studies have demonstrated the utility of serum albumin levels as a predictive factor for both nutritional status and inflammatory response in cancer patients." (PMID 38041687, 2024). "Over a decade ago, nanotechnology-based cancer drugs entered clinical trials, such as the albumin-bound paclitaxel nanoparticle used to treat metastatic breast cancer, which showed better efficacy and safety than solvent-formulated paclitaxel." (PMID 39136021, 2024). "The most significant confounding factors were taken into account in the analysis, including age, Charlson Comorbidity Index, year of surgery, pathologic cancer stage, surgical technique, type of gastrectomy, albumin, and BMI." (PMID 38153640, 2024). "Inflammatory cytokines derived from cancer cells can activate neutrophil proliferation, suppress lymphocytes, and increase the breakdown of proteins, including albumin." (PMID 39229553, 2024). "A previous study showed that due to high blood hemoglobin and albumin, angiogenesis increases protein contents and thus elevates APTw values in malignant tumors." (PMID 38298813, 2024). "The prognostic nutritional index (PNI) is a parameter calculated using albumin and absolute lymphocyte value, reflecting the immunological and nutritional status of the cancer patient." (PMID 39161499, 2024). "This supports our finding of CRP and albumin as early prognostic parameters at the time of cancer diagnosis." (PMID 38539528, 2024). "Results from a previous study also showed that serum albumin and prealbumin levels were lower in patients with cancer cachexia." (PMID 38438901, 2024). "Some studies have also combined albumin with other parameters to predict the prognosis of patients with cancer." (PMID 38438901, 2024). "A retrospective study demonstrated increased wound infection rates and mortality when accounting for factors such as age, preoperative hemoglobin, albumin, cancer stage and adverse pathological features." (PMID 39122993, 2024). "Complete blood count (FBC), C-reactive protein (CRP), and albumin can reflect the systemic inflammatory status of cancer patients and thus predict prognosis to some extent." (PMID 38279138, 2024). "CAR, was a combination of CRP and albumin, reflects the inflammatory state and nutritional state of cancer patients." (PMID 39098146, 2024). "Empirical evidence corroborates the significance of serum albumin levels as a potent prognostic indicator of cancer-related mortality across various patient cohorts and general populations." (PMID 38500655, 2024).
cancer (continued). "Nab-paclitaxel, a novel, chremophor-free 130-nm nanoparticle albumin-bound formulation, paclitaxel was transported and concentrated in cancer cells through serum albumin, which binds a specific receptor (gp60) on the endothelia, function as a carrier." (PMID 38709400, 2024). "A 70-year-old male was admitted to the Hubei Cancer Hospital complaining of left-side limb weakness and numbness for one month following the first cycle of albumin paclitaxel plus cisplatin plus tislelizumab regimen for the right-side NSCLC in December 2021." (PMID 39296984, 2024). "In conclusion, our developed ABCAP score, incorporating Altered Mental Status, BUN, Cancer, Albumin and Pulse as key variables, has demonstrated strong predictive performance in assessing the 30-day in-hospital mortality risk for older patients with UGIB." (PMID 38902633, 2024). "Low albumin levels, which indicate a lower nutritional condition, are common in cancer patients and are known to interfere with immune systems such humoral and cellular immunity and phagocytosis." (PMID 38384810, 2024). "The capability of the synthesized albumin conjugates 2 and 3 to shrink tumors was evaluated in anovarian cancer mouse model following systemic administration by intravenousinjection of the conjugates." (PMID 38345213, 2024). "An albumin-gold NP bionanosystem for selective targeting of albondin receptors (located on the membrane of malignant liver cancer cells) was tested for its efficacy in enhancing laser thermal ablation in a mouse hepatocellular carcinoma cell line." (PMID 39125610, 2024). "Serum albumin levels and cancer mortality are closely related, yet large-sample studies encompassing a broad spectrum of cancer types are lacking." (PMID 38500655, 2024). "Research indicates that serum albumin levels serve as an independent factor influencing the prognosis of patients with malignant tumors." (PMID 38966640, 2024). "Serum albumin is recognized as a biomarker for evaluating nutritional and inflammatory statuses in patients with cancer." (PMID 38473396, 2024). "This study aimed to investigate the clinical value of the glucose‐albumin ratio (GAR) in predicting the prognosis of cancer patients prescribed anthracycline‐based chemotherapy." (PMID 39660481, 2024). "Traditional metabolic indicators (such as serum albumin (ALB), prealbumin (PA), and body mass index (BMI)) have been well implicated in various cancers, including HCC." (PMID 38390261, 2024). "Prealbumin has also been proven to be an effective prognostic predictor for cancer patients, with higher sensitivity than albumin in predicting the nutritional status of patients." (PMID 38707705, 2024). "Laboratory markers such as albumin offer an affordable and accessible way to assess the nutritional status of individuals with cancer." (PMID 39195131, 2024). "The ability of albumin to be biodistributed across cancer cells and the ability of these cells to internalize the protein have been demonstrated." (PMID 38255859, 2024). "Additionally, while albumin and bilirubin are surrogate markers of liver function, they are not distinctly associated with any known oncogenic pathway and thus do not mechanistically explain the relationship between their preoperative levels and cancer prognosis." (PMID 38398089, 2024). "In view of the proven efficacy of serum albumin NCs for cancer therapy, their potential for the direct delivery of anti-cancer drugs by inhalation has been explored." (PMID 38543241, 2024). "The low albumin level in patients with cancer is due to increased catabolism, and the cachexia state of patients with cancer leads to increased vascular permeability and increased albumin loss." (PMID 39132507, 2024). "Multivariate survival analysis showed that age, BMI, DM, CVD, cancer, urine volume, HGB, ALB, and PE were independent predictors for all-cause mortality." (PMID 38415296, 2024).
cancer (continued). "It is known that inflammatory markers such as lymphocytes, neutrophils and albumin have prognostic importance in cancer patients." (PMID 39768966, 2024). "The optimal cutoff value of albumin, prealbumin, and transferrin for cancer cachexia patients in our study was 38.7 g/L, 0.17 g/L, and 2.29 g/L, respectively, as calculated by standardized log-rank statistics." (PMID 38438901, 2024). "Cancer treatment resulted in an increase in prealbumin and albumin levels (p < 0.001) and a reduction in CRP levels (p < 0.001), with no change in UAMA (p = 1.000)." (PMID 39619813, 2024). "Proposed mechanisms for low albumin in cancer patients include the production of inflammatory cytokines like IL-6 and increased vascular permeability, which raises the transcapillary escape rate of albumin, reducing serum levels." (PMID 39385181, 2024). "In 2014, the Haipeng Liu team introduced the “albumin hitchhiking” strategy, enhancing lymph node enrichment of cancer vaccines through optimized amphiphiles and offering a novel direction for lymph node-targeted vaccines." (PMID 39188723, 2024). "The predictive value of indicators such as the C-reactive protein-to-albumin ratio, the fibrinogen-to-albumin ratio, and others in the treatment of malignant tumors has also been successively reported." (PMID 38707705, 2024). "Albumin-coated gold nanoparticles display potential biomedical applications, including cancer research, infection treatment, and wound healing; however, elucidating their interaction with normal cells remains an area with limited exploration." (PMID 39452583, 2024). "The Glasgow Prognostic Score and modified Glasgow Prognostic Score using a combination of serum albumin and C-reactive protein have been reported in relation to postoperative prognosis in many cancers." (PMID 39594844, 2024). "The role of serum albumin (ALB) has been extensively studied in patients with cancer; however, research on its effect on bone metastasis in these patients remains limited." (PMID 38552093, 2024). "The presented data demonstrate considerable potential for in situ albumin targeting in the development of siRNA-based, carrier-free cancer therapies." (PMID 39598570, 2024). "The individual blood test results most strongly predictive of cancer in symptomatic patients were low albumin, high platelets, high PSA, and high CA125." (PMID 39078806, 2024). "It has been reported in studies conducted on many types of cancer that hemoglobin, albumin, lymphocyte, platelet (HALP) score can be a new prognostic predictor." (PMID 39061000, 2024). "This study is the first to explore the relationship between serum albumin levels and cancer-related mortality across a diverse array of cancer types in a substantial sample size." (PMID 38500655, 2024). "Background and Objectives: The HALP (Haemoglobin, Albumin, Lymphocyte and Platelet) score is used to predict the prognosis of different types of cancer." (PMID 39768966, 2024). "The human serum albumin nanostructures deliver indocyanine green to induce PTT in ablation of cancer metastasis and provide cancer imaging." (PMID 39346915, 2024). "Specifically, the effect of TyG-related indices on all-cause mortality of the MetS population differed among subgroups defined by age, gender, race, marital status, history of cancer, and serum levels of ALB, ALT, AST, BUN, TC, and UA." (PMID 38658993, 2024). "A decreased level of ALB is correlated with excess systemic inflammation that affects cancer progression." (PMID 38443675, 2024). "Prior studies have indicated the superior performance of the CONUT score over albumin alone in predicting outcomes in a variety of patients, including cancer patients." (PMID 39123455, 2024). "Accumulating studies have also confirmed that prealbumin and transferrin were effective for survival prediction in patients with cancer, even with a better performance than albumin." (PMID 38438901, 2024).